BEGAIN (brain enriched guanylate kinase associated)
Description:
May sustain the structure of the postsynaptic density (PSD).
Synonyms: KIAA1446
Tractability: Antibody: UniProt places it where antibodies can reach, with medium confidence. PROTAC: ubiquitination databases record sites on it.
Gene: Protein-coding gene on chromosome 14 (100,537,147 to 100,587,417, reverse strand). Ensembl gene ENSG00000183092.
Subcellular location: Cytoplasm; Membrane
Subcellular location (Human Protein Atlas): Nucleoplasm; Cytosol; Golgi apparatus
Pathways (Reactome):
Neuronal System: Neurexins and neuroligins
Gene Ontology:
Molecular function: protein binding
Biological process: evoked excitatory postsynaptic potential
Cellular component: synapse; cytoplasm; membrane; postsynapse
Genetic constraint (gnomAD): Loss-of-function variants: 22 observed, 32.69 expected, observed/expected ratio (o/e) 0.67, 90% interval 0.48 to 0.96. The synonymous counts are far from expectation, so gnomAD's model fits this gene poorly and the ratio says little. Missense variants: 795 observed, 716.77 expected, observed/expected ratio (o/e) 1.11, 90% interval 1.05 to 1.18. Synonymous variants: 462 observed, 341.35 expected, observed/expected ratio (o/e) 1.35, 90% interval 1.25 to 1.46.
Homologues: Orthologues: chimpanzee BEGAIN (97% identical), macaque BEGAIN (97% identical), dog BEGAIN (92% identical), rat Begain (87% identical), mouse Begain (86% identical), pig BEGAIN (85% identical), tropical clawed frog begain (55% identical).
Diseases named in the same sentence as BEGAIN in open-access papers:
BEGAIN is named in the same sentence as 9 diseases in open-access papers, as found by Europe PMC text mining. Sharing a sentence is not in itself a finding about the gene and the disease. The quoted sentences say what the papers report.
autism (1 paper, 2023). Persistent deficits in social interaction and communication and interaction as well as a markedly restricted repertoire of activity and interest as well as repetitive patterns of behavior. "The first experimental evidence comes from a methylation array screen, reporting the BEGAIN locus to be hypomethylated in the brain of individuals with autism." (PMID 38019471, 2023). "The male-specific hypomethylation of the BEGAIN promoter in blood, and by extrapolation other somatic tissues is exaggerated in males suffering from autism." (PMID 38019471, 2023).
neuroblastoma (1 paper, 2022). Neuroblastoma (NB) is the most common solid, extracranial childhood tumor. "Low tumour expression is associated with better survival in neuroblastoma patients, and incidentally, upon ATRA treatment, we found BEGAIN expression is downregulated in differentiating cell lines but not in SH-EP, where it is upregulated." (PMID 36147741, 2022).
peripheral nerve injury (1 paper, 2016). Injury to a peripheral nerve. "Collectively, these results suggest that BEGAIN was involved in neuropathic pain after peripheral nerve injury." (PMID 27785460, 2016).
neurodevelopmental disorder (1 paper, 2023). A behavioral and cognitive disorder with onset during the developmental period that involves impaired or aberrant development of intellectual, motor, or social functions. "It is tempting to speculate that transmission of paternal age-associated sperm methylation changes into the next generation modulates BEGAIN regulation and susceptibility to neurodevelopmental disorders." (PMID 38019471, 2023). "The observation that BEGAIN is hypomethylated in the brain of children with autism spectrum disorder (ASD), compared to controls, provides additional evidence for its role in the etiopathogenesis of neurodevelopmental disorders." (PMID 38019471, 2023).
BEGAIN also shares sentences with these, for which no sentence is quoted: breast carcinoma (3 papers); cancer (2); tumour (2); breast tumor (1); metastatic tumours (1).